CD44 (CD44 molecule (IN blood group))
Diseases named in the same sentence as CD44 in open-access papers (continued):
Sharing a sentence is not in itself a finding about the gene and the disease.
cancer (continued). "In a multivariate analysis, the percentage of CD44+/CD24− cancer cells was an independent factor related to metastasis development (p = 0.004)." (PMID 23028444, 2012). "Flow cytometry was then performed using the human TIC surface markers Lin-, CD24 and CD44, which importantly have also been implicated in TIC characteristics in luminal cancers specifically." (PMID 22765220, 2012). "To examine the chemoresistance of CD44+ cells to anti-cancer chemotherapeutic agents, we performed cell survival assays for the CD44+ and CD44− cell fractions treated with fluorouracil (5-FU), cisplatin or doxorubicin." (PMID 23285037, 2012). "Recently a small subset of cancer cells was identified by their cell surface markers (e.g., up-regulation of CD44 and down-regulation of CD24) as cancer stem cells (CSCs)." (PMID 23226410, 2012). "TNBCs are a difficult to treat subgroup of cancers that have been observed to express high levels of CD44." (PMID 22937154, 2012). "Expression analysis of selected cancer-relevant genes revealed down-regulation of CD44 as a common response to the combined treatments." (PMID 23227266, 2012). "44±35), with 46/74 (62.2%) cases expressing CD44 in ⩾40% of cancer cells and thus considered as being positive." (PMID 22333601, 2012). "Previous work has reported the podoplanin and CD44 double positive cells possess cancer stem cell properties in A431 cell line." (PMID 22745808, 2012). "In contrast, we showed that mammosphere culture of CD44− cells enriched for CD44+ cancer stem-like cells through an EMT process." (PMID 22134360, 2012). "Flow cytometry was used to study the co-expression of EpCAM with putative cancer stem cell markers, such as CD44, CD24, and ABCG2, in RB primary tumors." (PMID 22328825, 2012). "In combination with other surface markers, CD44 can also discriminate between a variety of cancer subsets." (PMID 22693526, 2012). "Previous studies indicate ALDH is a more specific HNSCC CSC marker than CD44, as ALDH expression identifies a subpopulation of CD44 positive cells containing the tumorigenic cancer stem cells." (PMID 23176396, 2012). "The percentage of cancer cells with membranous CD44 expression ranged from 0 to 100% (median 40, mean±s.d." (PMID 22333601, 2012). "CD166 has also been suggested to play a critical role in various human cancers and as a potential therapeutic target for cancer initiating cells, similar to CD44 and CD47." (PMID 22880034, 2012). "CD44 is expressed in almost all normal and cancer cells leading to discrepancy and reflecting the ambiguity regarding functional aspects of CD44 in CSC maintenance and mechanisms involved in cross-talk with expression of stemness genes." (PMID 22693526, 2012). "The association of CD44 and CD147 with MCT transporter proteins has been documented for different cancers." (PMID 22870202, 2012). "EpCAM was co-expressed with all cancer stem cell markers (CD44, CD24, and ABCG2) in primary RB tumors." (PMID 22328825, 2012). "We investigated the expression of four markers that have previously been described for isolation of several types of human CSCs in human cancer cell lines: CD44, CD24, ABCG2, and EpCAM." (PMID 22328825, 2012). "The close association of CD44, CD24 and Oct4 with cancer cell proliferation highly supports the assumption that these are indeed markers of clonogenic cells." (PMID 22333601, 2012). "Our initial findings provide the basis for further studies to examine how the dynamic morphology and the motion of cancer cells are modulated in a CD44 isoform-dependent manner." (PMID 22916191, 2012). "We also observed that STAT3 expression in cancer stem cells (CD44+CD24–/low subpopulation) of MCF-7 cells was much higher than that in MCF-7 cells." (PMID 23554768, 2012). "All the experimental work was performed on cell lines, and so it cannot be interpreted in relation to any possible CD44 positive cancer stem cell phenotype." (PMID 22242150, 2012).
cancer (continued). "Similar to CD44, we confirmed the presence of putative cancer stem cell marker CD29, but the expression on sphere and mono-layer cells of both cell lines was almost identical." (PMID 23042145, 2012). "In particular, luminal-type carcinomas (A and B) showed a significantly lower percentage of CD44+/CD24− cells compared to other immunotypes." (PMID 23028444, 2012). "In all events, exposure of CD44+ cancer stem-like cells to irradiation after a 4-hour DMF + BSO treatment resulted in a triggering of the intrinsic apoptotic pathway as efficiently as in the whole SQ20B cell population." (PMID 21283807, 2011). "Earlier studies have identified a subpopulation of putative cancer stem cells (CSCs) with the phenotype CD44+/CD24-/low and more recently, aldehyde dehydrogenase (ALDH) activity was shown to mark normal as well as malignant mammary stem cells." (PMID 21957977, 2011). "Here we present data to suggest that the analysis and study of CD44 expression in cancer development should take the presence of various isoforms into account." (PMID 21957977, 2011). "Of all patients tested, 39 patients had between 1–5% CD44+ cancer cells, 38 patients had >5–10% CD44+ cells, 19 patients had >10–20% CD44+ cells, 9 patients had >20–50% CD44+ cells, and 11 patients had >50% CD44+ cells." (PMID 21904548, 2011). "Expression of CD44 is widely identified in cancer stem cells in various organs, such as breast, colon, and pancreas." (PMID 21915300, 2011). "The existence of P63+/AR-, CK14+/AR- and CD44+/AR- progeny indicates direct procurement of AR- malignant cancer trait." (PMID 21241512, 2011). "In conjunction with hypoxia, increases in extracellular spermine specifically augmented hypoxia-induced decreases in CD44 expression, and these decreases correlated well with increased migration of cancer cells (HT-29) in a dose-dependent manner." (PMID 21988863, 2011). "Although cancer tissues produce vascular growth factors, their deregulated growth induces hypoxia, which in turn enhances polyamine uptake by cancer cells to further augment cell migration and suppress CD44 expression." (PMID 21988863, 2011). "During inflammation and in cancer patients serum levels of soluble CD44 are significantly increased." (PMID 22216242, 2011). "Similar results were obtained when CD44 RNA expression levels were compared with the presence of cells with the putative cancer stem cell phenotype CD44+/CD24-." (PMID 21957977, 2011). "CD44 also plays a role in cell migration, differentiation, and survival signaling, which is important both to normal cells and cancer cells." (PMID 21749678, 2011). "We further established an inverse significant correlation between BRCA1 expression levels and CD44+ cancer cell phenotype (p=0.02)." (PMID 23508738, 2011). "During EMT, epithelial cells express markers such as CD44, which are known to be expressed in cancer stem cells." (PMID 22069487, 2011). "Genes associated with the metastatic ability of cancer stem cells, especially Muc-1, MMP9 and Myc, were strongly reduced by CD44 knockdown." (PMID 22152097, 2011). "Reduced CD44 expression is reported to promote cancer metastasis and invasion, allowing detachment of cancer cells from the primary tumor cluster and seems to contribute to the increased migration capacity of hypoxic HT-29 cells." (PMID 21988863, 2011). "To identify the relationship of mammosphere formation and cancer stem cell population, we carried out flow cytometry using the cancer stem cell markers (CD44+/ CD24−/low)." (PMID 22132214, 2011). "CD44 has been reported to play an important role in cancer cell invasion and metastasis as well as in fundamental biological processes, including lymphocyte homing, hematopoiesis, inflammation, wound healing, and apoptosis." (PMID 21819617, 2011). "Down-regulation of some key signaling pathway genes proved that CD44 knockdown BCSCs underwent phenotypic changes from cancer stem cells to cancer cells or normal cells." (PMID 22152097, 2011).
cancer (continued). "Associations between the mRNA expression of CD44 isoforms and the cancer stem cell phenotypes CD44+/CD24- and ALDH1+ (as determined by IHC)." (PMID 21957977, 2011). "These cells have elevated levels of the cell surface marker CD44 in a variety of cancers, including OSCC." (PMID 22132151, 2011). "When we have considered the properties common to these proteins that have apparently no functional relationship with one another, we noticed that AL1A1, AK1C1, AK1C3 and CD44 have been proposed to be the markers of cancer stem cells." (PMID 21888658, 2011). "Considering the results of our study, the expression of CD44 of normoxic cancer cells is higher than that of hypoxic cells, suggesting that the circulating cancer cells possibly recover their original adhesion characteristics." (PMID 21988863, 2011). "Regarding cell adhesion molecules, the down-regulation of CD44 expression is reported to correlate with metastasis and poor prognosis in various types of carcinoma." (PMID 21473743, 2011). "The results of this study clearly show that a major function of HER2 is to increase the frequency of CD44+/high/CD24- cancer stem cells." (PMID 21044318, 2010). "To characterize the primary cultures of cancer-associated fibroblasts, we examined the expressions of the stromal cell-associated surface markers CD10, CD105, CD44 and CD54 on 32 primary cultures of fibroblasts by flow cytometry." (PMID 20711432, 2010). "Integrin αvβ3 and CD44 are receptors of osteopontin and CD44 is frequently over expressed in cancer cells." (PMID 20868520, 2010). "These experiments illustrate that the interaction between OPN and either CD44 or integrin is sufficient to induce phosphorylation of Akt, which is largely responsible for the anti-apoptotic mechanisms vital to cancer cell survival and progression." (PMID 20868520, 2010). "Numerous studies have demonstrated that both CD133+ and CD44+ cells are highly tolerant to anti-cancer therapies, and moreover, the number of CSCs can be significantly increased after treatment." (PMID 20630067, 2010). "293T cells readily form spheres that are enriched with cancer stem cell surrogates ALDH1 and CD44+/CD24- and express the proteins associated with the epithelial-mesenchymal transition and stem cell developmental pathways." (PMID 20615238, 2010). "Initially, we investigated the expression of the cancer stem cell markers Cd34, Cd24a, Cd44, Cd133, Cd90, Podoplanin (Pdpn), Nestin (Nes) and Discs, large homolog 7 (Drosophila) (Dlg7)." (PMID 21152443, 2010). "We, amongst others, have shown that cancer cells that have undergone epithelial to mesenchymal transition (EMT) display the CD44+/CD24- phenotype." (PMID 20691079, 2010). "Mechanistically, invasive and metastatic growth can be mediated through the interaction of cell surface CD44 with extracellular matrix components such as hyaluronan with subsequent changes induced in the cytoskeletal machinery of cancer cells." (PMID 21124918, 2010). "We report that 293T cell readily form spheres that are enriched with cancer stem cell surrogates ALDH1 and CD44+/CD24- cells and express proteins associated with the epithelial-mesenchymal transition and stem cell developmental pathways." (PMID 20615238, 2010). "Although CD44+/CD24- cells were originally described as CSCs, in the same original study, CD44+/CD24+ cancer cells isolated from one patient with comedo (more aggressive) type adenocarcinoma were tumorigenic." (PMID 20691079, 2010). "Taken together, the high egfr copy number MDA-MB-468 CD44+/CD24-/LOW cells represent cancer cells with a higher potential for survival, esp." (PMID 20199686, 2010). "Both ArLa and JIMT-1 represent highly treatment resistant cancer types, the latter featuring also an enrichment of the CD44+/CD24−/low containing the CIC cell types." (PMID 21079774, 2010).
cancer (continued). "Osteopontin (OPN) is a secreted phosphoprotein which functions as a cell attachment protein and cytokine that signals through two cell adhesion molecules, αvβ3-integrin and CD44, to regulate cancer growth and metastasis." (PMID 19570203, 2009). "Recent contradictory reports on widespread versus restricted expression pattern of CSC marker CD44 in HNSCC has opened up discussion to identify novel CSC markers in this cancer type." (PMID 19399189, 2009). "Most of the metastatic lesions and matched primary cancer tissues expressed high levels of uPA, CD44 and MDR1." (PMID 19603017, 2009). "In HBCx-3 a very strong CD44 staining was found in cancer cell islets near within the necrotic areas." (PMID 19240712, 2009). "In contrast to CD133, CD44 was expressed to a weaker extent in human cancer cells in xenograft tissue and colospheres than in spheroids." (PMID 19603013, 2009). "Despite the limited sample size, the data revealed an overall trend that the cancer specimens with higher numbers of CD44+/CD24−/low cells express low level of HER2." (PMID 20027313, 2009). "In breast, colon, and HNSCC, CD44-positivity was a discriminative characteristic of cancer-initiating cells." (PMID 18852874, 2008). "Alternatively, the number of CD44+/Flk-1+ cells is initially increased, but then these cells rapidly convert into CD44-/Flk-1- cancer cells." (PMID 19087284, 2008). "Given this recent evidence, we sought to determine if human prostate CD44+CD24− cells defined a population of cancer stem cells." (PMID 18268494, 2008). "Flk-1 is specifically expressed in CD44+ cells, suggesting that stem-like cancer cells are protected by DC-induced elevation of Flk-1." (PMID 19087284, 2008). "The cancer stem cells isolated from tumors are mostly isolated by flow cytometry as the CD44+ CD24-/low lineage cell population." (PMID 19014671, 2008). "Immunoreactivities to Ki-67, EMMPRIN, and VEGF were weaker in IT carcinoma than in the MT intestinal portion (p < 0.05), while the opposite was true for CD44, MUC-2, and MUC-6 (p < 0.05)." (PMID 18266006, 2008). "Immunoreactivities to Ki-67, EMMPRIN, and VEGF were weaker in the intestinal-type carcinomas than in the intestinal component of the MT (p < 0.05), while it was the opposite for CD44, MUC-2, and MUC-6 (p < 0.05)." (PMID 18266006, 2008). "The higher values of CD44 expression in the intratumoral hypoxic areas, especially in infiltrating malignant tumours, are also likely to reflect such biological functions in the neoplastic model." (PMID 17222331, 2007). "The results of VEGF-C were reproduced with CD44, with enhancement of statistically significant differences, especially in benign and malignant tumours." (PMID 17222331, 2007). "The exons in the 5′ and 3′ regions of CD44 are constitutively spliced, while ten exons in the middle of the gene undergo extensive alternative splicing in various tissues and cancers." (PMID 17183719, 2006). "Similar inhibition of binding by antibodies that recognize β1 integrins and CD44 isoforms suggests that integrins participate in the adhesion of cancer cells to endothelial cells." (PMID 16859559, 2006). "For example, cleavage of CD44 by MMP-14 results in increased motility in different cancer cell lines and mutation of the putative MMP-14 cleavage site in CD44 inhibits migration." (PMID 14612884, 2003). "For example, CD44 and galectin 3, genes relevant for cancer metastasis, were up-regulated in peritoneal metastasis." (PMID 12402156, 2002). "ABE also reduced cancer stemness, as evidenced by reduced CD44, Nanog, and Oct4 expression." (PMID 41754803, 2026). "In consequence of the evolution of novel cell models and the research conducted in this article, we have established sophisticated pertinent models for the testing of novel antitumor molecules, encompassing targeted drugs that are directed towards the CD44 cancer stem cell marker." (PMID 41597220, 2026).
cancer (continued). "CD44-targeted nanocarriers might potentially impact the immune response to cancer by regulating the interactions between cancer cells and immune cells." (PMID 41367861, 2025). "HA carbon quantum dots (CQDs) exhibit several advantageous properties, including a high surface area-to-volume ratio, small particle size, biocompatibility, and low cytotoxicity, making them ideal for biomedical applications, such as CD44-targeted drug delivery in ferroptosis-based cancer therapy." (PMID 40363642, 2025). "Consequently, CD44 is a promising therapeutic target for various cancers, including prostate, colon, breast, ovarian, and pancreatic cancers." (PMID 40001633, 2025). "CD44 is often considered a cancer stem cell marker, and its expression is induced by EMT." (PMID 40940864, 2025). "In addition, we found that the strength of the magnetic field and the concentration of CD44 micro beads affect the ability of the cancer cells captured." (PMID 40821671, 2025). "•Some cancer stem markers are CD44, HLA-I, pan-cytokeratin, and EGFR." (PMID 40738059, 2025). "Moreover, intact nuclear CD44/STAT3 signaling has been shown to be critical for reprogramming cancer cells to a CSC phenotype through the transcriptional regulation of c-myc expression and the subsequent self-renewal of CSCs." (PMID 39851489, 2025). "Consequently, the development of anti-CD44 mAbs capable of selectively recognizing individual variants is crucial for elucidating CSC biology and developing variant-specific cancer therapy." (PMID 41009730, 2025). "CD44, a nonkinase transmembrane glycoprotein, is implicated in the progression of several cancers, including ccRCC." (PMID 39815326, 2025). "Immunohistochemical examinations have shown that HA and CD44 frequently co-localize in bone metastases of certain cancer cells, suggesting that CD44-mediated capture may increase the local concentration of HA in bone metastases." (PMID 40176023, 2025). "By disrupting CD44 turnover at the cell surface, these therapies may effectively reduce cancer cell migration and metastatic potential, offering new hope for improving patient outcomes." (PMID 41440277, 2025). "In addition, we used qRT‐PCR to evaluate the effects of miRNA-383 and cisplatin on CD44 gene expression (as a marker for cancer stem cells)." (PMID 40751520, 2025). "Furthermore, the research results showed that Cur@(Zn–Adenine)@HA NPs achieved targeted delivery and controlled release of Cur through the specific binding of HA to the highly expressed receptor CD44 on the surface of cancer cells." (PMID 40733206, 2025). "RBM47 modulates the splicing of CD44, which is a marker of cancer stem cells." (PMID 40695891, 2025). "CD44 is expressed by embryonic stem cells and a variety of cell types, with multiple isoforms depending on the tissue, and is also heightened in certain cancer cell subpopulations, serving as a molecular marker for cancer stem cells (CSC)." (PMID 40221767, 2025). "These discrepancies could potentially be attributed to small sample sizes and the role of different CD44 isoforms in cancer progression and behavior." (PMID 41465166, 2025). "In this study, we confirmed that cation–π interactions and electrostatic interactions between sodium hyaluronate and DOX could successfully develop self-assembled HA/DOX nanoaggregates for enhancing CD44-overexpressing-cancer-cell therapy." (PMID 39997114, 2025). "CD44 is a promising candidate for predicting the prognosis of patients with malignant tumors." (PMID 40240758, 2025). "Moreover, CD44 has been identified as a marker for cancer-initiating cells, also known as cancer stem cells, in various malignancies of haematopoietic and epithelial origins." (PMID 40544280, 2025). "Notably, studies indicate that upon the addition and interaction of HGF with CD44v6 expressing cancer cells, there is an increase in the number of CD44-HGF-bound dimers and in the diffusion coefficient in the plasma membrane of such complexes." (PMID 40114966, 2025).